TERF1 (telomeric repeat binding factor 1)
Diseases named in the same sentence as TERF1 in open-access papers:
TERF1 is named in the same sentence as 103 diseases in open-access papers, as found by Europe PMC text mining. Sharing a sentence is not in itself a finding about the gene and the disease. The quoted sentences say what the papers report.
breast carcinoma (29 papers, 2007 to 2025). "TERF1 is a target of miR-155, and this microRNA can inhibit its expression and promotes carcinogenesis in breast cancer." (PMID 34486082, 2021). "In a population-based study of 1995 breast cancer cases and 2296 controls from Poland, 24 SNPs representing common variation in POT1, TEP1, TERF1, TERF2 and TERT were genotyped." (PMID 17848914, 2007).
neuroblastoma (13 papers, 2016 to 2022). Neuroblastoma (NB) is the most common solid, extracranial childhood tumor. "Higher expression of miR-155 and lower levels of TERF1 was observed in neuroblastoma tissues with higher TAM infiltration." (PMID 36793342, 2022). "MiR-155 directly targets TERF1 and affect telomerase activity and telomerase length in neuroblastoma." (PMID 36793342, 2022). "In turn, the TAMs secrete miR-155 in exosomes, which targets telomeric repeat binding factor 1 (TERF-1) in neuroblastoma cells, thereby increasing telomerase activity and subsequently cisplatin resistance." (PMID 33672261, 2021). "Exosomal miR-155 was then transferred back to neuroblastoma cells, where it silenced telomeric repeat binding factor 1 (TERF1) and resulted in increased resistance to cisplatin in chemotherapy." (PMID 33233600, 2020). "Macrophage-derived EVs containing miR-155 are transferred back to neuroblastoma cells where miR-155 acts on its target, telomeric repeat-binding factor 1 (TERF1, a telomerase inhibitor)." (PMID 30884898, 2019). "miR-155 in turn released by mononuclear cells can be taken up by neuroblastoma cells, reducing expression of the telomerase inhibitor telomeric repeat-binding factor 1 (TERF1), enhancing the activity of telomerase and promoting drug resistance in tumor cells." (PMID 29302403, 2017). "Once taken up by neuroblastoma cells, miRNA-155 targeted the telomeric repeat-binding factor 1 (TERF1) inducing an increased growth when the cells were treated with cisplatin." (PMID 27282631, 2016). "miR-155 could then be passaged back to the tumor cells via EVs downregulating the miR-155 target telomeric repeat binding factor 1 (TERF1), a telomerase inhibitor, with subsequent upregulation of telomerase which promotes neuroblastoma drug resistance." (PMID 36498469, 2022). "MiR-155 and TERF1 expression levels were also assessed in 20 primary neuroblastoma tissues." (PMID 36793342, 2022). "Fascinatingly, miR-21 containing EVs from neuroblastoma cells induced the release of monocyte EVs containing miR-155 which in turn induced cisplatin resistance on neuroblastoma cells, by entering these cells and repressing TERF1, both in vitro and in vivo." (PMID 32384712, 2020). "The silencing of TERF1 induces increased resistance to cisplatin in neuroblastoma cells." (PMID 30884898, 2019). "Interestingly, miR-155 is also transferred from monocytes to neuroblastoma via EVs and induces chemoresistance in neuroblastoma through targeting telomeric repeat binding factor 1 (TERF1)." (PMID 27582126, 2017). "This enhanced cisplatin resistance in neuroblastoma cells by entering these cells and inhibiting TERF1 (telomeric repeat binding factor 1)." (PMID 35159299, 2022). "EV-miR-21 from neuroblastoma cells is transferred to monocytes, which can differentiate into macrophages, and upregulates miR-155 expression by binding TLR8; the educated monocytes in turn secrete EV-miR-155 to induce chemotherapy resistance by targeting TERF1 in neuroblastoma cells." (PMID 32503543, 2020).
glioblastoma (10 papers, 2013 to 2025). The most malignant astrocytic tumor (WHO grade IV). "We identified an increase in expression of TEP1, TERF1, and TERF2IP in glioblastoma and astrocytoma cell lines compared to HDFa and NHA control cell lines." (PMID 36142793, 2022).
lung fibrosis (8 papers, 2016 to 2025). "Six1 was also upregulated in bleomycin-treated (BLM-treated) mice and in a model of spontaneous lung fibrosis driven by deletion of Telomeric Repeat Binding Factor 1 (Trf1) in AT2 cells." (PMID 35420997, 2022).
colorectal cancer (6 papers, 2016 to 2023). A primary or metastatic malignant neoplasm that affects the colon or rectum. "Increased or high level TERF1/TRF1 expression has been observed in a large percentage of adult T-cell leukemia and colorectal cancer samples." (PMID 27148394, 2016).
prostate carcinoma (4 papers, 2020 to 2024). A carcinoma that arises from epithelial cells of the prostate gland. "TERF1 has the potential to become a biomarker in prostate cancer." (PMID 34486082, 2021). "Our results corroborate that miR-155 regulates TERF1 expression in prostate cancer." (PMID 34486082, 2021).
leukemia (3 papers, 2019 to 2022). A malignant (clonal) hematologic disorder, involving hematopoietic stem cells and characterized by the presence of primitive or atypical myeloid or lymphoid cells in the bone marrow and the blood. "Interestingly, we also observed the expression of TERF1-tsi in (healthy)-donor-derived CD34+-HSCs but not in the CD34+-KG1 cell line or other leukemia cell lines such as HL60 or U937 (unpublished observations)." (PMID 31877678, 2019).
lung adenocarcinoma (3 papers, 2015 to 2023). A carcinoma that arises from the lung and is characterized by the presence of malignant glandular epithelial cells. "Other telomere maintenance genes showed limited evidence of colocalisation with lung adenocarcinoma (i.e. TERF1 and PIF1)." (PMID 37079368, 2023). "Alternately, TERF1 (an homologue of TERF2 present in the shelterin complex) and TERF2 expression levels were directly related to survival in lung adenocarcinoma (TERF2, disease free survival; P = 0.0097) and lung squamous cell carcinoma (TERF1, overall survival; P = 0.0065)." (PMID 27329590, 2016).
melanoma (3 papers, 2012 to 2021). A malignant, usually aggressive tumor composed of atypical, neoplastic melanocytes. "It has, however, been shown that at least one SNP pair at the TERF1 and the AFAP1L2 loci does interact to affect risk of melanoma." (PMID 34903281, 2021).
promyelocytic leukemia (3 papers, 2014 to 2024). "Our data confirm this notion describing co-localization of the phosphorylated form of telomeric repeat-binding factor 1 (pT371-TRF1) with ALT-associated promyelocytic leukemia bodies." (PMID 36140400, 2022).
renal carcinoma (2 papers, 2021 to 2024). A carcinoma arising from the epithelium of the renal parenchyma or the renal pelvis. "In particular, TERF1 overexpression was found strongly correlated with TL and disease progression in gastric and renal carcinomas." (PMID 34944968, 2021). "Shelterin expression predicted patient survival in 24 cancer types, with TERF1, TERF2, TINF2, and POT1 significantly expressed in testicular, AML, prostate, breast and renal cancers, respectively, and TPP1 in AML and skin cancer." (PMID 39578854, 2024). "TERF1, TERF2, TINF2, and POT1 are significantly expressed in testicular, Acute Myeloid Leukemia (AML), prostate and breast as well as renal cancers, respectively." (PMID 39578854, 2024).
colon cancer (1 paper, 2021). "Hence, our data highlights a mechanistic role near the TERF1 gene locus with telomere length and incident colon cancer risk, specific to the East Asian population." (PMID 33941849, 2021). "They find that three East Asian specific variants at POT1, TERF1 and STN1 loci are associated with leukocyte telomere length and report a mechanistic pathway linking TERF1, leukocyte telomere length and incident colon cancer." (PMID 33941849, 2021).
Hyperglycemia (1 paper, 2024). An increased concentration of glucose in the blood. "Hyperglycemia enhances DNA damage in MSCs; hence, we assessed the expression of DNA repair markers XRCC5, TERF1, CDKN1A, and SIRT1 in ASCs in a diabetic milieu." (PMID 38880916, 2024).
metastatic prostate carcinoma (1 paper, 2021). A carcinoma that arises from the prostate gland and has spread to other anatomic sites. "The expression of TERF1 mRNA levels was assessed utilizing TCGA datasets, clinical specimens, and metastatic prostate cancer cell lines (LNCaP, DU145, and PC3)." (PMID 34486082, 2021).
myositis (1 paper, 2025). "Telomere shortening in lymphocytes was present in SSc patients with TERF1 positivity, but the antibody was rarely detected in the sera of RA and myositis patients." (PMID 40629711, 2025). "Brittany tested a group of CTD patients with RA, SSc, and myositis for Telomeric Repeat Binding Factor 1 (TERF1)." (PMID 40629711, 2025). "It was found that the frequency of TERF1 positivity was higher in SSc patients than in RA, myositis, and healthy controls." (PMID 40629711, 2025). "However, TERF1 is rarely detected in the sera of patients with RA and myositis." (PMID 40629711, 2025).
osteosarcoma (1 paper, 2018). A usually aggressive malignant bone-forming mesenchymal neoplasm, predominantly affecting adolescents and young adults. "Here, we track bulk chromatin movements of intranuclear proteins in U2OS human osteosarcoma cells transfected with fibrillarin (GFP-Fibrillarin) or telomeric repeat-binding factor 1 (RFP-TRF1)." (PMID 30591710, 2018).
pituitary adenoma (1 paper, 2024). "Genetic associations with pituitary adenoma occurrence: the TERF1 rs1545827 CT + TT genotypes were linked to 2.9-fold decreased odds of PA occurrence." (PMID 38339395, 2024). "Serum TERF1 levels were measured in patients with pituitary adenoma (n = 40) and the reference group (n = 60)." (PMID 38339395, 2024). "TERF1 rs1545827, TNKS2 rs10509637 and rs10509639, TERF2 rs251796, ZNF676 rs412658, and CTC1 rs3027234 genes’ single nucleotide polymorphisms were analyzed to evaluate the associations with pituitary adenoma relapse." (PMID 38339395, 2024).
seminoma (1 paper, 2019). A radiosensitive malignant germ cell tumor found in the testis (especially undescended), and extragonadal sites (anterior mediastinum and pineal gland). "Moreover, we could detect TERF1/PIN2 proteins in seminoma tumor samples when pan-TERF1 antibody was used (ab1423)." (PMID 31877678, 2019). "Our study also revealed that TERF1-tsi expression was low or absent in human seminomas, testicular germ cell tumors likely arising from spermatogonia." (PMID 31877678, 2019). "On the other hand, TERF1-tsi expression was not detectable in the seminoma tumor sample when the TERF1-tsi specific antibody was used (AB2), in contrast to its expression in normal testis spermatogonia." (PMID 31877678, 2019). "TERF1-tsi was also absent in the TCam-2 cell line, the only available seminoma cell line available." (PMID 31877678, 2019). "However, it is also likely that seminoma may arise from TERF1-tsi negative cells and thus TERF1-tsi positive spermatogonia may be underrepresented in the tumor samples." (PMID 31877678, 2019). "Moreover, TERF1-tsi expression was also absent from the established seminoma cell line, TCam-2." (PMID 31877678, 2019).
systemic sclerosis (1 paper, 2024). A chronic disorder, possibly autoimmune, marked by excessive production of collagen which results in hardening and thickening of body tissues. "Analysis of peripheral blood leukocytes in systemic sclerosis patients revealed a negative association between TERF1 autoAbs and telomere length." (PMID 39616399, 2024). "Furthermore, a subset of patients diagnosed with systemic sclerosis had higher autoAbs targeting the telomere/shelterin complex, including the telomeric repeat-binding factor 1 (TERF1) as the most common autoantigen." (PMID 39616399, 2024).
testicular tumors (1 paper, 2019). "Either testicular tumors arise from TERF1-tsi negative spermatogonia, or alternatively, TERF1-tsi expression is downregulated during tumorigenesis." (PMID 31877678, 2019).
testis cancer (1 paper, 2019). "In order to evaluate the potential contribution of the TERF1-tsi to testis cancer, we analyzed its expression by RT-PCR and IHC." (PMID 31877678, 2019). "Interestingly, weak TERF1-tsi downregulation was observed in testicular cancer sample #3, which is histologically defined as intratubular germ cell neoplasia (ITGN)." (PMID 31877678, 2019).
uterine cancer (1 paper, 2020). Primary or metastatic malignant neoplasm involving the uterine corpus and/or the cervix. "The publicly available “The Cancer Genome Atlas” (TCGA) cohort of uterine cancers dataset suggests high expression of TRF1 gene (TERF1 RNA) in ECs to be associated with decreased survival." (PMID 33217925, 2020).
cancer (80 papers, 2010 to 2025). A tumor composed of atypical neoplastic, often pleomorphic cells that invade other tissues. "Paradoxically, cancer cells (CCs) require adequate shelterin to sustain their rapid proliferation, and increased levels of shelterin proteins such as TERF1, TERF2, and TINF2 are associated with tumour development." (PMID 39578854, 2024). "TERF1 is a gene essential to telomere maintenance, and its dysfunction has already been associates with several cancers." (PMID 34486082, 2021). "Only for cancer mortality we observed that the minor G allele of rs79617270 at TERF1 region, which was associated with increased telomere length, was associated with increased cancer mortality [HR95%CI = 1.544 (1.173, 2.032), Cox regression PAdj = 0.018]." (PMID 33941849, 2021). "Irrespective of the role of TERF1-tsi in stem-cell-derived cancers, it is therefore important to determine the differential expression of the TERF1 splice variants in the cancer context." (PMID 31877678, 2019). "Terf1 deficiency could increase telomere fragility and cancer in mice." (PMID 29216888, 2017). "Expression of TERF1 has previously been shown to have significant overexpression or downregulation, dependent on cancer type." (PMID 35054812, 2022). "Knockdown of SRSF2 in HCC cells resulted in alternatively spliced variants in cancer-related genes including exon inclusion of GCH1, STK39 and TERF1 (TRBF1)." (PMID 31162605, 2019). "By binding to TLR8, exo-miR-21 activates NF-κB signaling in TAMs, leading to transactivation of miR-155, which is then released as an exo-miRNA and is shuttled back to cancer cells, where it increases resistance to cisplatin by directly targeting TERF1." (PMID 28672799, 2017). "Recently, increasing evidence suggests that telomere maintenance genes, such as TERT, TERC, TERF1, TERF2, TINF2, TERF2IP and POT1 are associated with cancer risk." (PMID 22970196, 2012). "More recently, the substrate repertoire of AKT has been expanded to include telomeric repeat binding factor 1 (TRF1), a member of the telomere-bound shelterin complex, which is hyperactivated in cancer cells, and endows them with limitless replicative potential." (PMID 39614261, 2024). "Additionally, the work of Marcos and colleagues has indicated that TERF1 is deregulated in the context of cancer development, underscoring its relevance in the broader field of oncology." (PMID 38339395, 2024). "TERF1 is found to be significantly correlated with the highest number of cancers." (PMID 39578854, 2024). "Previous publications indicate the deregulated expression of TERF1 in cancer." (PMID 31877678, 2019). "Besides, KG1 cells, in addition to the TCam-2 cells offer another option for functional studies to address the role of TERF1-tsi in cancer." (PMID 31877678, 2019). "Changes in several shelterin components, such as TERF2, TERF1, and TINF2, have been identified in human cancers, highlighting potential therapeutic targets to combat cellular ageing and telomerase activity in various cancers." (PMID 39578854, 2024). "Subsequently, TAM-derived exosomes, enriched for miR-155, travel back to the tumor, and, upon uptake by cancer cells, miR-155 binds to TERF1 (Telomeric Repeat Binding Factor 1) mRNA." (PMID 29652798, 2018). "There is a positive correlation between TERF1 and androgen receptor expression in cancer tissue (r = 0.53, p < 0.00001) but not on normal tissue (r = - 0.16, p = 0.12)." (PMID 34486082, 2021).
tumor (45 papers, 2007 to 2026). "Consistent with our data, the ratio of PTPMT1 E3 and SMARCD1 E5 exclusion was decreased in tumor samples compared to paired normal samples, while TERF1 E7 exhibited the opposite AS trend." (PMID 33992102, 2021). "In order to evaluate telomerase activity specifically in CSCs, we compared the expression levels of TERT and TERF1 in CSCs versus bulk tumor cells in three human PDX-derived primary PDAC cell lines (Panc215, Panc185, Panc354)." (PMID 34201898, 2021). "In our recent study, we showed that NB‐secreted miR‐21 in exosomes induces chemotherapy resistance through another oncogenic miR‐155 within the tumor microenvironment by targeting TERF1, an inhibitor of the telomerase axis." (PMID 31637848, 2020). "Both RT-PCR and IHC show a specific downregulation of TERF1-tsi in tumor samples while the expression of TERF1 and PIN2 remains unchanged." (PMID 31877678, 2019). "In a first attempt to evaluate the impact of TERF1-tsi in the testis, we have tested its expression in normal testis samples versus matched tumor samples from the same patients." (PMID 31877678, 2019). "On the other hand, in the absence of cultured cells with endogenous TERF1-tsi, ectopic expression of this splice variant in TCam-2 cells will be a suitable tool to gain further insights into TERF1-tsi in cell proliferation and tumor suppression." (PMID 31877678, 2019). "It would be interesting to find out whether TERF1-tsi is expressed in a subset of human CD34+ HSC population and whether its expression is downregulated during tumor progression." (PMID 31877678, 2019). "Importantly, TERF1-tsi is expressed in normal testis samples but absent in matched tumor samples from the same patients indicating a potential role of TERF1-tsi in tumor suppression." (PMID 31877678, 2019).
TERF1 also shares sentences with these, for which no sentence is quoted: infection (15 papers); lung carcinoma (14); gastric cancer (6); glioma (6); renal cell carcinoma (5); aplastic anemia (4); breast tumor (3); Obesity (3); renal fibrosis (3); bladder cancer (2); dyskeratosis congenita (2); heart failure (2); idiopathic pulmonary fibrosis (2); lung squamous cell carcinoma (2); lymphoma (2); nematode infection (2); skin cancer (2); telomere syndrome (2); acne (1); acute myeloid leukaemia (1); age-related macular degeneration (1); Alzheimer disease (1); anemia (1); angiosarcoma (1); astrocytoma (1); autism (1); benign prostate hyperplasia (1); Bloom syndrome (1); brain tumours (1); Burkitt lymphoma (1).
A further 49 diseases each share a sentence with TERF1 in 1 paper.